LAT2 (linker for activation of T cells family member 2)
Description:
Involved in FCER1 (high affinity immunoglobulin epsilon receptor)-mediated signaling in mast cells. May also be involved in BCR (B-cell antigen receptor)-mediated signaling in B-cells and FCGR1 (high affinity immunoglobulin gamma Fc receptor I)-mediated signaling in myeloid cells. Couples activation of these receptors and their associated kinases with distal intracellular events through the recruitment of GRB2.
Synonyms: LAB; NTAL; WBSCR15; WBSCR5; HSPC046; WSCR5
Tractability: Antibody: UniProt places it where antibodies can reach, with high confidence; its Gene Ontology location is reachable by antibodies, with high confidence; UniProt predicts a signal peptide or a membrane-spanning region; the Human Protein Atlas places it where antibodies can reach. PROTAC: UniProt records ubiquitination sites on it; ubiquitination databases record sites on it; its protein half-life has been measured.
Gene: Protein-coding gene on chromosome 7 (74,199,652 to 74,234,454, forward strand). Ensembl gene ENSG00000086730.
Subcellular location: Cell membrane
Subcellular location (Human Protein Atlas): Plasma membrane
Pathways (Reactome):
Immune System: Role of LAT2/NTAL/LAB on calcium mobilization
Gene Ontology:
Molecular function: protein binding; SH2 domain binding
Biological process: B cell activation; B cell receptor signaling pathway; calcium-mediated signaling; intracellular signal transduction; immune response-regulating signaling pathway
Cellular component: extracellular exosome; membrane raft; plasma membrane
Genetic constraint (gnomAD): Loss-of-function variants: 22 observed, 43.88 expected, observed/expected ratio (o/e) 0.5, 90% interval 0.36 to 0.72. The upper end of that interval is the gene's LOEUF score, 0.72, which puts it in group 2 of 6, group 1 being the genes least tolerant of losing a copy. Missense variants: 284 observed, 316.5 expected, observed/expected ratio (o/e) 0.9, 90% interval 0.81 to 0.99. Synonymous variants: 128 observed, 125.44 expected, observed/expected ratio (o/e) 1.02, 90% interval 0.88 to 1.18.
Homologues: Orthologues: chimpanzee LAT2 (98% identical), macaque LAT2 (92% identical), dog LAT2 (62% identical), pig LAT2 (61% identical), guinea pig LAT2 (58% identical), rat Lat2 (51% identical), mouse Lat2 (50% identical).
Diseases named in the same sentence as LAT2 in open-access papers:
LAT2 is named in the same sentence as 82 diseases in open-access papers, as found by Europe PMC text mining. Sharing a sentence is not in itself a finding about the gene and the disease. The quoted sentences say what the papers report.
pancreatic cancer (9 papers, 2018 to 2025). "Among them, high expression of L‐type amino acid transporter 2 (LAT2) leads to abnormal amino acid uptake and metabolism, causing rapid proliferation in pancreatic cancer, osteosarcoma, and other tumor cells." (PMID 39778021, 2025). "Conversely, LAT2 expression was associated with poorer survival in pancreatic cancer and was indicated to play a role in the pathogenesis of glomerulonephritis, both through LAT2-mediated mTOR activation." (PMID 36438828, 2022). "Our study demonstrated that a high LAT2 level was associated with poor overall survival in pancreatic cancer." (PMID 30419950, 2018). "Multivariate analysis demonstrated that a high level of LAT2 was an independent risk factor for poor prognosis in pancreatic cancer (P = 0.017)." (PMID 30419950, 2018). "Next, we found that gemcitabine combined with an mTOR inhibitor (RAD001) could reverse the decrease in chemosensitivity caused by LAT2 overexpression in pancreatic cancer cells." (PMID 30419950, 2018). "In this study, we have demonstrated that RAD001 treatment could reverse the decrease in GEM sensitivity caused by LAT2 overexpression in pancreatic cancer." (PMID 30419950, 2018). "SLC7A8 or LAT-2 is an L-type amino acid transporter-2 protein that binds and regulates mechanistic target of rapamycin kinase (mTOR) activation in pancreatic cancer." (PMID 32235589, 2020). "LAT2 is a member of the L-type amino acid transporter family, and its oncogenic role in the chemoresistance of pancreatic cancer has been recently reported by our group previous research." (PMID 31514732, 2019). "We found that GSTM3TV2 promoted pancreatic cancer gemcitabine resistance by upregulating LAT2 and OLR1 though competitively sponging let-7." (PMID 31514732, 2019). "To identify the effects of LAT2 on apoptosis in pancreatic cancer cells, we detected the apoptosis rate and apoptosis-related protein changes induced by LAT2 KD/OE in MIA PaCa-2 and PANC-1 cells." (PMID 30419950, 2018). "Univariate analysis indicated that lymph node staging (P = 0.049), differential degree (P = 0.002) and LAT2 expression level (P = 0.008) were the potential predictive factors for poor prognosis in pancreatic cancer." (PMID 30419950, 2018). "We also confirmed the role of LAT2 in glycolysis and glutamine metabolism in pancreatic cancer cells." (PMID 30419950, 2018). "We also demonstrated that the decreased apoptosis and increased ECAR and glycoPER induced by the LAT2-mTOR-LDHB pathway in pancreatic cancer cells were dependent on glutamine." (PMID 30419950, 2018). "This diagram shows the mechanisms by which LAT2 regulates glycolysis and gemcitabine sensitivity in pancreatic cancer." (PMID 30419950, 2018). "Previous studies have shown that LAT2 was overexpressed in gemcitabine-resistant pancreatic cancer cells." (PMID 30419950, 2018). "To demonstrate the role of LAT2 in gemcitabine sensitivity in pancreatic cancer, we carried out growth inhibition assays to test the chemosensitivity of pancreatic cancer cells to gemcitabine in vitro and in vivo." (PMID 30419950, 2018). "Then, the intracellular level of glutamine was determined by UHPLC-MS/MS, and the results showed that the intracellular level of glutamine was upregulated in pancreatic cancer cells with LAT2 OE." (PMID 30419950, 2018). "In summary, these data indicate that LAT2 promotes pancreatic cancer cell proliferation in vitro and in vivo." (PMID 30419950, 2018). "The results revealed that the expression level of LAT2 in the pancreatic cancer tissues was higher than that in the paracancerous tissues." (PMID 30419950, 2018). "The expression level of LAT2 in 87 pancreatic cancer tissue samples and 71 matched paracancerous tissues was evaluated by immunohistochemistry (IHC)." (PMID 30419950, 2018). "Taken together, these results suggest that LAT2 decreases the gemcitabine sensitivity of pancreatic cancer cells in vitro and in vivo." (PMID 30419950, 2018).
pancreatic cancer (continued). "For example, LAT2 as an oncogene could weaken the sensitivity of pancreatic cancer cells to gemcitabine." (PMID 34976784, 2021). "LAT2 is overexpressed and plays a carcinogenic role in pancreatic cancer." (PMID 33456463, 2020). "Consistently, LAT2 and OLR1 were direct targets of let-7 families, and GSTM3TV2 could upregulate the expression of LAT2/OLR1 in pancreatic cancer cells via competitively sponging let-7." (PMID 31514732, 2019). "Thus, all these results confirmed the critical role of GSTM3TV2 in gemcitabine resistance of pancreatic cancer cells via LAT2 and OLR1." (PMID 31514732, 2019). "We then investigated that GSTM3TV2 could promote pancreatic cancer gemcitabine resistance by upregulating L-type amino acid transporter 2 (LAT2) and oxidized low-density lipoprotein receptor 1(OLR1) though competitively sponging let-7." (PMID 31514732, 2019). "We also assessed the role of LAT2 in proliferation by LAT2 KD/OE in pancreatic cancer cells." (PMID 30419950, 2018). "Then, we investigated whether the process by which LAT2 targets mTOR activation to regulate apoptosis, glycolysis and chemosensitivity in pancreatic cancer cells was dependent on glutamine." (PMID 30419950, 2018). "In this study, we identified LAT2 as a novel oncogenic protein in pancreatic cancer." (PMID 30419950, 2018). "The results revealed that both ECAR and glycoPER were increased in the LAT2 OE pancreatic cancer cells compared with the control cells and that this increase could be reversed by RAD001 treatment." (PMID 30419950, 2018). "LAT2 is upregulated in 9 different cancer types according to Oncomine data; however, few studies have proved its specific role in cancer, and the expression level and role of LAT2 in pancreatic cancer remain uncertain and elusive." (PMID 30419950, 2018). "We demonstrated that LAT2 emerged as an oncogenic protein and could decrease the gemcitabine sensitivity of pancreatic cancer cells in vitro and in vivo." (PMID 30419950, 2018). "We also explored the correlation between the LAT2 level and the prognosis of pancreatic cancer." (PMID 30419950, 2018). "In this study, we also demonstrated that LAT2 played an oncogenic role in pancreatic cancer and could decrease GEM sensitivity by regulating the glutamine-dependent LAT2-mTOR-LDHB pathway." (PMID 30419950, 2018). "LAT2 suppressed apoptosis in pancreatic cancer cells with LAT2 OE; this suppression could be reversed by RAD001 treatment." (PMID 30419950, 2018). "Thus, we presumed that LAT2 might be involved in the development and regulation of chemoresistance in pancreatic cancer." (PMID 30419950, 2018). "Therefore, the LAT2-mTOR-LDHB pathway might be a promising therapeutic target in pancreatic cancer, and further study should be conducted to investigate the specific mechanisms between the two positive feedback loops." (PMID 30419950, 2018). "The LAT2-mTOR-LDHB pathway might be a promising therapeutic target in pancreatic cancer." (PMID 30419950, 2018). "Simultaneously, RAD001 could increase the GEM sensitivity of LAT2 OE pancreatic cancer cells." (PMID 30419950, 2018). "However, the role of LAT2 in chemoresistance in pancreatic cancer remains uncertain and elusive." (PMID 30419950, 2018). "The results indicated that RAD001 could downregulate glutamine synthetase in MIA PaCa-2 and PANC-1 cells and that the levels of both p-mTORSer2448 and glutamine synthetase are decreased in pancreatic cancer cells with CRISPR/Cas9-mediated knockout of LAT2 (LAT2 KO)." (PMID 30419950, 2018). "Finally, GEM combined with RAD001 could increase GEM sensitivity in pancreatic cancer patients with LAT2 OE." (PMID 30419950, 2018). "Binding with miR-let-7 in the cell cytoplasm, lncRNA GSTM3TV2 served as a ceRNA to up-regulate LAT2 and OLR1 expression, promoting cell gemcitabine resistance in pancreatic cancer." (PMID 33442418, 2021).
pancreatic cancer (continued). "We observed that LAT2 and OLR1 were upregulated in gemcitabine-resistant pancreatic cell lines and that inhibiting their expression enhanced the chemosensitivity of pancreatic cancer cells to gemcitabine." (PMID 31514732, 2019). "To identify the effects of mTOR on glycolysis in pancreatic cancer cells, we then detected ECAR and glycoPER in MIA PaCa-2 and PANC-1 cells with LAT2 OE that were treated with RAD001." (PMID 30419950, 2018). "The results of a survival analysis indicated that high expression levels of both LAT2 and LDHB predicted a poor prognosis in patients with pancreatic cancer." (PMID 30419950, 2018). "We found that the expression levels of both LAT2 and LDHB in pancreatic cancer tissues were higher than those in the paracancerous tissues and that high levels of both LAT2 and LDHB were associated with poor prognosis." (PMID 30419950, 2018). "(D, E) Kaplan-Meier survival analysis indicated that the overall survival rate of the high-LDHB and high-LAT2 level group is poorer than that of pancreatic cancer patients with other LDHB and LAT2 statuses (P = 0.0044)." (PMID 30419950, 2018). "Taken together, our data reveal that LAT2 functions as an oncogenic protein and could regulate glutamine-dependent mTOR activation to promote glycolysis and decrease GEM sensitivity in pancreatic cancer." (PMID 30419950, 2018). "In humans, the specific role of LAT2 in pancreatic cancer has not been reported and is still elusive." (PMID 30419950, 2018). "Otherwise, GEM could induce apoptosis in pancreatic cancer cells, and RAD001 could reverse the inhibition of apoptosis induced by GEM in pancreatic cancer cells with LAT2 OE." (PMID 30419950, 2018). "Consequently, LAT2 interacts with p-mTORSer2448 to activate glycolysis, increase the intracellular level of glutamine and decrease the GEM sensitivity of pancreatic cancer cells." (PMID 30419950, 2018). "Our previous study has demonstrated that the expression level of LAT2 in AsPC-1-GEM cells is higher than that in the parental cells, which might indicate that LAT2 plays an important role in chemoresistance in pancreatic cancer." (PMID 30419950, 2018). "Next, to validate whether GSTM3TV2 modulated LAT2 and OLR1 to promote chemoresistance in pancreatic cancer, we constructed the specific siRNAs targeting LAT2 and OLR1 (siLAT2 and siOLR1, respectively) to silence the expression of LAT2 and OLR1 in MIAPaCa-2/GR and Rv-AsPC-1-GSTM3TV2 cells." (PMID 31514732, 2019). "Mechanistically, LAT2 could regulate the glutamine/p-mTORSer2448/glutamine synthetase feedback loop to keep mTOR activated and to upregulate LDHB in order to activate glycolysis, thereby promoting chemoresistance in pancreatic cancer cells." (PMID 30419950, 2018). "In addition, high levels of both LAT2 and LDHB are poor prognostic predictors in pancreatic cancer." (PMID 30419950, 2018). "Mechanistically, we demonstrated that LAT2 could regulate two glutamine-dependent positive feedback loops (the LAT2/p-mTORSer2448 loop and the glutamine/p-mTORSer2448/glutamine synthetase loop) to promote glycolysis and decrease gemcitabine (GEM) sensitivity in pancreatic cancer." (PMID 30419950, 2018). "In addition, LAT2 could decrease GEM sensitivity, promote proliferation, inhibit apoptosis and activate glycolysis in pancreatic cancer cells, and these effects could be reversed by RAD001 treatment." (PMID 30419950, 2018). "Consequently, our data indicate that the LAT2-mTOR-LDHB pathway might be a valuable prognostic predictor and promising therapeutic target in pancreatic cancer." (PMID 30419950, 2018). "In conclusion, we have demonstrated that LAT2 could regulate two glutamine-dependent positive feedback loops (the LAT2/p-mTORSer2448 loop and the glutamine/p-mTORSer2448/glutamine synthetase loop) to promote glycolysis and decrease GEM sensitivity in pancreatic cancer." (PMID 30419950, 2018).
glioma (7 papers, 2014 to 2025). A benign or malignant brain and spinal cord tumor that arises from glial cells (astrocytes, oligodendrocytes, ependymal cells). "Further studies should investigate homogeneous glioma groups and additionally analyse LAT2 expression levels and the complex SLC-transporter family in more detail." (PMID 34905134, 2021). "18F-FET uptake mechanism is driven by glioma overexpression of the active transmembrane L-type amino-acid transporter 2 (LAT2) and, to a minor extent, the lesser glioma-specific LAT1." (PMID 34671551, 2021). "Irrespective of the IDH status, 18F-FET PET false negativity may depend on low cellularity of GR, on small-sized viable glioma components, on GR low or defective expression of amino-acid transporter LAT2." (PMID 34671551, 2021). "All three amino acid radiotracers accumulate in gliomas and brain metastases due to increased transport by LAT1 and LAT2." (PMID 40710005, 2025). "For instance, in U87-MG glioma and A549 cells, alanine uptake is facilitated by SNAT1, SNAT2, SNAT5, SLC6A15 (B0AT2), SLC7A6 (y+LAT2), SLC1A4 (ASCT1), and SLC1A5 (ASCT2), and many of these transporters are also involved in glutamine transport." (PMID 40716744, 2025). "The amino acid transport system L for large neutral amino acids, namely the subtypes LAT1 and LAT2, are responsible for the increased uptake of MET, FET and FDOPA in gliomas and brain metastases." (PMID 39355021, 2023). "In the glioma-infiltrated cortex, neurons also showed a pronounced expression of LAT1/LAT2/CD98, in particular where glioma cells were adjacent to neurons." (PMID 33291423, 2020). "Other reports have confirmed the expression of LAT1 at the blood-brain barrier (BBB), however, expression of LAT2 in the BBB is controversial and limited information exists regarding LAT2 expression in gliomas." (PMID 24918622, 2014). "In a rat C6 glioma cell line, LAT1, but not LAT2, was expressed, and in normal astrocytes LAT2, but not LAT1, was expressed, indicating LAT1 as a possible target for anti-cancer therapy." (PMID 24918622, 2014).
leukemia (7 papers, 2014 to 2023). A malignant (clonal) hematologic disorder, involving hematopoietic stem cells and characterized by the presence of primitive or atypical myeloid or lymphoid cells in the bone marrow and the blood. "These splicing perturbations alter the composition of numerous hematopoietic stem and progenitor (KLF2, GATA2, GATA1, SPINK2) or leukemia (LAT2 and NUCB2) regulatory factors." (PMID 36697445, 2023). "Neo N termini (See Methods for definition) from leukemia-associated proteins such as PDK3 and LAT2 were elevated in relapse cases." (PMID 33722259, 2021). "Moreover, LAT2 interferes with differentiation of normal hematopoietic precursor cells, and recent studies highlight the role of LAT2 as a prognostic marker in other leukemia entities such as APL." (PMID 34331016, 2021).
cataract (5 papers, 2019 to 2025). Partial or complete opacity of the crystalline lens of one or both eyes that decreases visual acuity and eventually results in blindness. "Loss of the amino acid transporter LAT2 (Slc7a8) causes a strong imbalance in lens amino acid concentrations and is associated with cataracts in both mouse and humans." (PMID 32833997, 2020). "Heterozygous LAT2 variants were also found in patients with cataract some of which showed a reduced transport function when expressed in HeLa cells." (PMID 31231240, 2019). "Heterozygous LAT2 variants have also been found in patients with cataracts." (PMID 35887081, 2022). "We have shown that the lack of functional LAT2 provokes a strong decrease of lens essential amino acid levels in mice and furthermore associates with cataracts in both, mice and humans." (PMID 31231240, 2019). "Taken together, simultaneous absence of both transporters leads to increased occurrence in cataract in all groups, while the lack of LAT2 alone was sufficient to result in a significant increase of cataracts in old animals, in particularly in old females." (PMID 31231240, 2019). "Interestingly, the absence of LAT2 resulted in an increased incidence of cataracts in mice, particularly in older females." (PMID 35887081, 2022).